SORCS2 (sortilin related VPS10 domain containing receptor 2)
Description:
The heterodimer formed by NGFR and SORCS2 functions as receptor for the precursor forms of NGF (proNGF) and BDNF (proBDNF). ProNGF and proBDNF binding both promote axon growth cone collapse (in vitro). Plays a role in the regulation of dendritic spine density in hippocampus neurons (By similarity). Required for normal neurite branching and extension in response to BDNF. Plays a role in BDNF-dependent hippocampal synaptic plasticity. Together with NGFR and NTRK2, is required both for BDNF-mediated synaptic long-term depression and long-term potentiation. ProNGF binding promotes dissociation of TRIO from the heterodimer, which leads to inactivation of RAC1 and/or RAC2 and subsequent reorganization of the actin cytoskeleton. Together with the retromer complex subunit VPS35, required for normal expression of GRIN2A at synapses and dendritic cell membranes. Required for normal expression of the amino acid transporter SLC1A1 at the cell membrane, and thereby contributes to protect cells against oxidative stress (By similarity). [SorCS2 122 kDa chain]: Does not promote Schwann cell apoptosis in response to proBDNF. SorCS2 104 kDa chain and SorCS2 18 kDa chain together promote Schwann cell apoptosis in response to proBDNF.
Synonyms: KIAA1329
Tractability: Antibody: UniProt places it where antibodies can reach, with high confidence; UniProt predicts a signal peptide or a membrane-spanning region; its Gene Ontology location is reachable by antibodies, with medium confidence. PROTAC: its protein half-life has been measured.
Gene: Protein-coding gene on chromosome 4 (7,192,538 to 7,742,827, forward strand). Ensembl gene ENSG00000184985.
Subcellular location: Cell membrane; Cell projection; Cytoplasmic vesicle membrane; Early endosome membrane; Recycling endosome membrane; Synapse, synaptosome; Perikaryon; Cell projection, dendrite; Cell projection, dendritic spine; Postsynaptic density membrane
Subcellular location (Human Protein Atlas): Cytosol; Vesicles
Gene Ontology:
Molecular function: neuropeptide receptor activity; transmembrane signaling receptor activity
Biological process: neuropeptide signaling pathway; intracellular protein transport; long-term synaptic depression
Cellular component: cytoplasmic vesicle membrane; perikaryon; plasma membrane; early endosome membrane; membrane; postsynaptic density membrane; recycling endosome membrane; dendrite; dendritic spine; postsynaptic density; synapse
Genetic constraint (gnomAD): Loss-of-function variants: 98 observed, 118.6 expected, observed/expected ratio (o/e) 0.83, 90% interval 0.7 to 0.98. The synonymous counts are far from expectation, so gnomAD's model fits this gene poorly and the ratio says little. Missense variants: 1,580 observed, 1,402.2 expected, observed/expected ratio (o/e) 1.13, 90% interval 1.08 to 1.17. Synonymous variants: 754 observed, 598.21 expected, observed/expected ratio (o/e) 1.26, 90% interval 1.19 to 1.34.
Homologues: Orthologues: chimpanzee SORCS2 (99% identical), macaque SORCS2 (97% identical), pig SORCS2 (88% identical), mouse Sorcs2 (86% identical), rat Sorcs2 (86% identical), dog SORCS2 (84% identical), guinea pig SORCS2 (75% identical), tropical clawed frog sorcs2 (68% identical), zebrafish sorcs2 (64% identical). Paralogues in human: SORCS1 (42% identical), SORCS3 (42% identical), SORL1 (22% identical), SORT1 (17% identical).
Diseases named in the same sentence as SORCS2 in open-access papers:
SORCS2 is named in the same sentence as 45 diseases in open-access papers, as found by Europe PMC text mining. Sharing a sentence is not in itself a finding about the gene and the disease. The quoted sentences say what the papers report.
bipolar disorder (7 papers, 2014 to 2024). A disorder of the brain that causes unusual shifts in mood, energy, activity levels and the ability to carry out day-to-day tasks. "SORCS2 is another gene highly populated by pG4-BS regions (410 associated pG4-BS regions), whose mutations may carry the increased risk of reduced neuronal synaptic plasticity, bipolar disorder, attention deficit-hyperactivity disorder and schizophrenia." (PMID 37094040, 2023). "Although SorCS2 is known to play a crucial role in neuronal viability and function, human epidemiological studies have reported that single nucleotide polymorphisms in SorCS2 are associated with the risk of developing psychiatric disorders such as ADHD, bipolar disorder, and schizophrenia." (PMID 35145374, 2021). "One SCZ case showed a somatic copy number variant (sCNV) overlapping intron 1 and potentially exon 2 of SORCS2, implicated in attention-deficit hyperactive disorder (ADHD), and bipolar disorder, though roles of SORCS2 in SCZ are not established." (PMID 39388546, 2024). "Comparison with other published GWA studies for bipolar disorder, excluding those with partial overlap of subjects, appears to corroborate several loci and candidate genes, including CNTNAP5, ZNF804A, ZNF659, SORCS2, and ZNF536." (PMID 24387768, 2014).
Alzheimer disease (5 papers, 2016 to 2025). A progressive, neurodegenerative disease characterized by loss of function and death of nerve cells in several areas of the brain leading to loss of cognitive function such as memory and language. "Our findings are in keeping with the known involvement of other sortilin family members in cognition, ageing and neurodegenerative disorders and with the recent finding that SNPs in SORCS2 are involved in epistatic interactions associated with pathological hallmarks of Alzheimer’s disease." (PMID 34741697, 2023). "Genetic variation in SORCS2 has been associated with Alzheimer’s disease where the protein may affect the intracellular processing of amyloid precursor protein." (PMID 28346477, 2017). "We found that neutral ceramidase (ASAH2/ASAH2B) and sortilin-related VPS10 domain-containing receptor 2 (SORCS2) were significantly elevated in the serum of individuals who later developed Alzheimer's dementia." (PMID 40772191, 2025).
schizophrenia (5 papers, 2016 to 2023). A major psychotic disorder characterized by abnormalities in the perception or expression of reality. "To study how pathological conditions might affect SORCS2 expression, we compared CNS levels of total SORCS2 transcripts in patients suffering from autism or schizophrenia with healthy control groups using data from The Sequence Read Archive." (PMID 37507021, 2023). "Likewise, the variation was markedly increased in amygdala in patients suffering from schizophrenia compared to healthy individuals (p = 0.047), suggesting that SORCS2 brain expression could be perturbed in a general manner in patients suffering from psychiatric disorders." (PMID 37507021, 2023).
breast carcinoma (4 papers, 2019 to 2024). "According to the COSMIC database, PRPRN2 and SORCS2 point mutations were detected in ∼18% and ∼13% of breast cancer samples, and ∼26% and ∼16% of prostate cancer samples, respectively." (PMID 37094040, 2023). "Given that expression of SORCS2 mRNA is highly restricted to the nervous system and the kidneys, it is tempting to speculate that the function of relatively high levels of SORCS2 expression observed in basal-like breast carcinomas should be attributed to intragenic miRNA hsa-miR-4274." (PMID 31781574, 2019). "LAMA4-regulating miRNA miR-4274 and its host gene SORCS2 were highlighted as intermediate regulators of the expression levels of LAMA4, which correlated in a basal-like breast carcinoma sample subset of TCGA to the levels of SORCS2 negatively." (PMID 31781574, 2019). "Taken together, observations concerning LAMA4, its regulating miRNA miR-4274 and its host gene SORCS2, point at a substantial role played by secondary and tertiary effects produced by a transcriptional knockdown of IGFBP6 in basal-like breast carcinoma cells." (PMID 31781574, 2019). "Expression levels of the strongest co-regulated gene pair, SORCS2 as a host and LAMA4 as a target, correlated negatively (R = −0.57, p < 2.2 × 10−16), when analyzed in a basal-like breast carcinoma sample subset of TCGA (N = 190)." (PMID 31781574, 2019). "Importantly, increases in COL8A1, BGN, COL11A1, POSTN, MMP11 and SORCS2 and decreased LTBP4, PCOLCE2, LRRC17 and SDK1 have been identified in CAS and CAFs from human breast cancer and are consistently perturbed in stroma of canine and human mammary cancer." (PMID 37391533, 2023).
diabetes (4 papers, 2017 to 2024). "This suggests an essential implication: mutation of the SORCS2 gene is genetically related to diabetes." (PMID 38474730, 2024). "Furthermore, eight of the 17 CpG sites reside in genes (FSTL1, SORCS2, NRF1, DLC1, PPARGC1B, CHN2, NXPH1) that have prior known associations with obesity, diabetes, and the insulin pathway." (PMID 28068899, 2017).
Obesity (4 papers, 2017 to 2022). Accumulation of substantial excess body fat. "Similarly, SORCS2 methylation, which functions to regulate fasting insulin levels and secretion of insulin, was potentially associated with increased obesity at 36 months but was not statistically significant in this relatively small sample." (PMID 32059710, 2020).
amyloid (2 papers, 2022 to 2025). "Contrary to the situation in aged PDAPP/KO mice, δ secretase activity was not increased in young PDAPP/KO female animals at 12 weeks of age, indicating that induction of δ secretase activity in SORCS2-deficient brains aligns well with the appearance of profound amyloid and tau pathologies." (PMID 41173884, 2025). "Thus, the up-regulation of ANGPT1, SORCS2 and MMP2 in AD ONS cells is consistent with enhanced amyloid-associated degenerative effects." (PMID 36291125, 2022).
epilepsy (2 papers, 2019 to 2023). A brain disorder characterized by episodes of abnormally increased neuronal discharge resulting in transient episodes of sensory or motor neurological dysfunction, or psychic dysfunction. "Protein encoded by SORCS2 gene coordinates intracellular transport of the glutamate and cysteine transporter EAAT3 in the neurons, where it provides a degree of protection from oxidative stress and epilepsy-induced cell death." (PMID 31781574, 2019).
Stroke (2 papers, 2023). Sudden impairment of blood flow to a part of the brain due to occlusion or rupture of an artery to the brain. "Lower astrocytic expression was seen for SORCS2, supporting findings from mouse models that expression of this receptor in astrocytes is only induced during stress response, as in stroke." (PMID 37842085, 2023). "Additionally, SORCS2 has been found to facilitate the release of endostatin from astrocytes and regulate post-stroke angiogenesis." (PMID 38371897, 2023).
allergic asthma (1 paper, 2019). A asthma with a basis in a pathological type I hypersensitivity reaction. "In addition, multiple DMRs with five or more CpGs (EPX (eosinophil peroxidase), ACOT7, SORCS2 genes) were overlapping across phenotypes like FeNO, allergic asthma, environmental IgE sensitization, and total IgE." (PMID 31300640, 2019).
autism (1 paper, 2023). Persistent deficits in social interaction and communication and interaction as well as a markedly restricted repertoire of activity and interest as well as repetitive patterns of behavior. "Interestingly, SORCS2 expression levels spanned a much greater range for autism patients than the control group (p = 0.00011)." (PMID 37507021, 2023). "In autism patients, mean SORCS2 expression was non-significantly increased by ∼60% in prefrontal cortex." (PMID 37507021, 2023).
behavioral problems (1 paper, 2021). "Taken together, these findings suggest that SorCS2 gene methylation may induce both reduced GMV in the orbital gyrus and emotional behavioral problems, although the direct association between the two could not be confirmed in this study." (PMID 35145374, 2021).
depression (1 paper, 2025). "Our observations suggest that SORCS2 might be affected in CP-induced depression as well." (PMID 40157903, 2025).
hearing loss (1 paper, 2017). "We suggest that in cases where its locus is included in the deletion, SORCS2 is a second candidate gene that may underlie the sensorineural hearing loss in WHS through additional effects on hair bundle organisation." (PMID 28346477, 2017).
Huntington disease (1 paper, 2022). Huntington disease (HD) is a rare neurodegenerative disorder of the central nervous system characterized by unwanted choreatic movements, behavioral and psychiatric disturbances and dementia. "Indeed, SorCS2 has been functionally associated with Huntington’s disease via its interaction with mutated huntingtin protein and its impaired sorting." (PMID 36397124, 2022).
myocardial infarction (1 paper, 2024). Gross necrosis of the myocardium, as a result of interruption of the blood supply to the area, as in coronary thrombosis. "An intriguing discovery has been made regarding the first SNP (rs13146480) within the SORCS2 (sortilin-related VPS 10 domain-containing receptor 2) gene, where a minor allele is positively related to myocardial infarction in the group with NAFLD." (PMID 38474730, 2024).
myocardial ischemia (1 paper, 2018). A disorder of cardiac function caused by insufficient blood flow to the muscle tissue of the heart. "In mice, Sorcs2 is expressed in mesodermally derived structures of the heart prior to E15.5 as well as after myocardial ischemia." (PMID 30687393, 2018).
non-small cell lung carcinoma (1 paper, 2019). A group of at least three distinct histological types of lung cancer, including non-small cell squamous cell carcinoma, adenocarcinoma, and large cell carcinoma. "Furthermore, genetic polymorphisms of SORCS2 have been associated with decreased survival in non-small cell lung cancer patients." (PMID 30710127, 2019).
periodontitis (1 paper, 2026). An acute or chronic inflammatory process that affects the tissues that surround and support the teeth. "In our experimental results, we found that the protein expressions of proBDNF and receptor SorCS2 were significantly increased in periodontitis tissues and colocalized with the hPDLSC surface marker CD90." (PMID 41343965, 2026). "The protein levels of both proBDNF and its receptor SorCS2 were significantly upregulated in periodontitis tissues and involved in regulating the inflammatory expression level and osteogenic differentiation of hPDLSCs." (PMID 41343965, 2026). "Comprehensive preclinical toxicology studies (in periodontitis animal models) are also crucial for a comprehensive assessment of the safety and efficacy of SorCS2 inhibition." (PMID 41343965, 2026).
prediabetes (1 paper, 2023). "In our study, we also identified an intergenic SNP (rs9929651) between IRX3 and CRNDE, as well as multiple SORCS2 SNPs, that showed significant associations with HDL-C levels in individuals with prediabetes." (PMID 38371897, 2023).
Seizure (1 paper, 2017). A seizure is an intermittent abnormality of nervous system physiology characterized by a transient occurrence of signs and/or symptoms due to abnormal excessive or synchronous neuronal activity in the brain. "Likewise its proNT binding function may underlie an association of SorCS2 with epileptic seizures in mice." (PMID 28346477, 2017).
tauopathy (1 paper, 2025). Neurodegenerative disorders involving deposition of abnormal tau protein isoforms (tau proteins) in neurons and glial cells in the brain. "Remarkably, loss of SORCS2 also caused tauopathy-like phenotypes in aging PDAPP/KO females." (PMID 41173884, 2025).
Wolf-Hirschhorn syndrome (1 paper, 2017). Wolf-Hirschhorn syndrome (WHS) is a developmental disorder characterized by typical craniofacial features, prenatal and postnatal growth impairment, intellectual disability, severe delayed psychomotor development, seizures, and hypotonia. "In humans, SORCS2 is located on the distal short arm of chromosome 4 within a gene-rich region subject to large chromosomal deletions that are associated with Wolf-Hirschhorn syndrome (WHS), a rare multisyndromic disorder." (PMID 28346477, 2017).
psychiatric disorder (3 papers, 2021 to 2023). A disorder characterized by behavioral and/or psychological abnormalities, often accompanied by physical symptoms. "Genetic and functional studies implicate SORCS2 in cognitive function, as well as in neurodegenerative and psychiatric disorders." (PMID 34741697, 2023).
neurological disorders (2 papers, 2023 to 2024). "The SORCS2 gene is a member of the Vps10p protein family, and Vps10p is associated with neurological disorders in mammals." (PMID 38393094, 2024).
tumor (2 papers, 2019 to 2023). "Moreover, preliminary data point that negative correlation of expression levels for genes SORCS2 and LAMA4 is a phenomenon which is, indeed, specific to only this tumor type." (PMID 31781574, 2019).
SORCS2 also shares sentences with these, for which no sentence is quoted: attention deficit-hyperactivity disorder (3 papers); colorectal cancer (2); Arthritis (1); benign adenomas (1); brain disease (1); cancer (1); COVID-19 (1); dementia (1); essential tremor (1); fatty liver (1); gastric cancer (1); Hypertension (1); Intellectual disability (1); narcolepsy (1); neurodegenerative disease (1); ovarian carcinoma (1); periodontal disease (1); prostate carcinoma (1); triple-negative breast carcinoma (1).